PDK1 (pyruvate dehydrogenase kinase 1)
Diseases named in the same sentence as PDK1 in open-access papers (continued):
Sharing a sentence is not in itself a finding about the gene and the disease.
cancer (continued). "While PDK1 is less sensitive to DCA than PDK2 or PDK4 (PDK2 > PDK4 > PDK1 > PDK3), DCA reduced the abundance of PDK1 in cancer cells and fibroblasts, indicating that inhibition is not the only mechanism by which DCA reduces the PDK1 function." (PMID 34445316, 2021). "We determined that DCA reduced the abundance of PDK1 in breast (MDA-MB-231) and prostate (PC-3) cancer cells, while it suppressed both PDK1 and PDK2 in skeletal muscle cells (L6 myotubes)." (PMID 34445316, 2021). "Pyruvate dehydrogenase kinase-1 (PDK-1), a key mitochondrial enzyme overexpressed in many cancer cells, redirects glucose metabolism from oxidative phosphorylation toward aerobic glycolysis." (PMID 33664850, 2021). "We found that DCA reduced the protein abundance of PDK1 in MDA-MB-231 and PC-3 cancer cells and the protein abundance of PDK1 and PDK2 in L6 myotubes." (PMID 34445316, 2021). "PDK1, PDK2, PDK3, PDK4, PDP2, and PDPR genes can regulate the glucose metabolism and glycolysis of cancer cells." (PMID 34199666, 2021). "The activation/inhibition of the PDK1/AKT signaling pathway regulates the proliferation, invasion, metastasis, and survival of human cancer cells." (PMID 34868313, 2021). "PGK1 can also act as a protein kinase to phosphorylate pyruvate dehydrogenase kinase 1 (PDHK1), whose regulation coordinates glycolysis and the tricarboxylic acid (TCA) cycle in cancer metabolism and tumorigenesis." (PMID 34445528, 2021). "PDK1-pS241 is produced by the gene PDK1 according to the TCPA database and is overexpressed in many types of cancer." (PMID 33842538, 2021). "DOHH2 cells with the highest sensitivity to chidamide had high expression levels of genes involved in the PI3K/PDK1/AKT pathway, which is regulated in several human carcinomas, including lymphoid malignancies." (PMID 34926293, 2021). "Since then, many studies have demonstrated elevated levels of LDHA, MCTs and pyruvate dehydrogenase kinase 1 (PDK1) (which inactivates PDH), which are considered hallmarks of cancer cells." (PMID 31936895, 2020). "Further, RASSF1A overexpression augmented HIF-1α promoter occupancy and transactivation of PDK1, HK2 and LDHA in both smooth muscle cells and cancer cells." (PMID 31086178, 2019). "Thus, selective modulators of PDK1 may have utility as anti-cancer agents." (PMID 30734603, 2019). "In cancer cells, oncogenic tyrosine kinases (BCR-ABL, JAK2) are highly expressed and perform tyrosine phosphorylation of pyruvate dehydrogenase kinase 1 (PDHK1)." (PMID 31847192, 2019). "Knockdown of PDK-1 reverts the Warburg phenotype, diminishes the normoxic HIF-1α expression, hypoxic cell survival, invasion, and inhibits cancer development." (PMID 31803621, 2019). "Our findings showed a direct interaction between PDK1 and STAT3 that silencing PDK1 significantly down-regulated p-STAT3-Y705 in CRC cells, suggesting a significant role of STAT3 signaling on cancer metabolism." (PMID 31506552, 2019). "Recently, miR-375 has been found significantly downregulated in multiple types of cancer, and suppresses core hallmarks of cancer by targeting several important oncogenes like AEG-1, YAP1, IGF1R and PDK1." (PMID 31737116, 2019). "This altered metabolic program is due to expression of pyruvate dehydrogenase kinase-1 (PDK1), a target of HIF1a with VEGF and TWIST as downstream targets, enabling cancer cells to adapt to nutrient insufficiencies and hypoxia in the host stroma." (PMID 31641356, 2019). "Recently, hsa-miR-375 was found to be significantly downregulated in multiple types of cancer lines and to suppress core hallmarks of cancer by targeting several important oncogenes like AEG-1, IGF1R, and PDK1." (PMID 29930763, 2018). "Consistently, PDK1 is enriched in BCSC populations and is essential for the maintenance of cancer stem-like properties in vitro and in vivo." (PMID 29106390, 2018).
cancer (continued). "High glycolytic rates in drug-resistant cells are often accompanied with higher expression of glycolytic regulators such as PDK1 and LDHA, making these enzymes interesting targets for drug-resistant cancers." (PMID 30456204, 2018). "The downregulated genes were associated with cell cycle, TGF-β signaling, FoxO signaling, HIF-1 signaling, and cancer (CDKN1B, FLT3, PDK1, FOXO1, BCL2, ERG), suggesting potential positive regulation of these pathways by SHARP1 to maintain MLL-AF6 AML activity." (PMID 29692408, 2018). "On account of that PDK1 is a normal upstream of AKT pathway, and AKT pathway is an important regulator in cancer stem cell." (PMID 29416606, 2018). "Instead, PDK1 was post-transcriptionally regulated by Wnt/β-catenin signaling via the Lin28-Let-7 pathway in NPC cells, which reflects the tissue specificity and cancer-type dependence." (PMID 29764469, 2018). "Pyruvate dehydrogenase kinase 1 (PDK1), which blocks oxidative respiration, was found to be the key Wnt target promoting aerobic glycolysis in these cancer cells." (PMID 28649368, 2017). "Since PDK1 comprises the most crucial effector downstream of KRAS, it is the best alternative for targeted therapy in this type of cancer." (PMID 29064423, 2017). "Both PDK1 and the lactate transporter MCT-1 are Wnt/beta-catenin targets and are overexpressed in cancer cells." (PMID 28298922, 2017). "In this study, we showed for the first time that DIC potently inhibits the kinase activity of PDK1 in a cell-free biochemical reaction system, in cultured SKOV3 and A2780 cancer cells in vitro, and in SKOV3 xenografts in vivo." (PMID 28617852, 2017). "Many of these kinases are involved in the deregulated activation of the MEK/ERK and PI3K/AKT pathway, including PDK1 and Casein kinase II, CK2, with involvement in chemotherapeutic drug resistance, proliferation of cancer initiating cells and angiogenesis." (PMID 26871292, 2016). "show that PDK1 activates SGK1 to phosphorylate and inhibit TSC2, contributing to maintenance of mTORC1 activity and resistance of PIK3CA-mutant cancer cells to PI3Kα inhibition." (PMID 27451907, 2016). "Myc and HIF1A are the best-known transcriptional regulators controlling expression of glycolysis genes, such as GLUT1, HK2, PDK1, and LDHA, whose expression levels are highly elevated in cancer cells." (PMID 26989077, 2016). "Several other studies demonstrated that expression of PDK1 induces EMT, anchorage-independent growth in vitro, increased proliferation, migration and invasion of cancer cells." (PMID 27551332, 2016). "As both PVs and cancer cells depend on activated PDK1 signaling and as host cells can overcome limitations to PV replication through malignant transformation, we suspected that the newly discovered mechanism might be active in human cancer cells and contribute to the natural oncotropism of PVs." (PMID 25742010, 2015). "Similar to PDK1, interference with HK2 does not only affect cellular metabolism, but also induces apoptosis thereby conferring a growth advantage to cancer cells." (PMID 25932951, 2015). "Inhibition of PDK1 or PDK3 impairs cell growth and increases oxygen consumption in human cancer cell lines." (PMID 25601413, 2015). "Based on our findings that PDK1 expression is closely related to the prognosis of GBC, additional studies of PDK1 and JunB as cancer biomarkers are warranted." (PMID 26318166, 2015). "PDH kinase 1 (PDK1), which phosphorylates and inactivates PDH, is frequently overactivated in cancer cells, resulting in an impaired TCA cycle and mitochondrial hyperpolarization." (PMID 24212624, 2011). "The mTORC2 pathway plays a key part of activating Akt, like PDK1(3-phosphoinositide-dependent protein kinase 1) and PI3K, a potential drug target for cancers in which there is Akt deregulation." (PMID 20929525, 2010).
cancer (continued). "In this study, we provide further evidence that PDK-1 is upregulated in hypoxia and that it is under the control of the HIF-1 transcription factor in HNSCC cell lines and many other cancer cell types." (PMID 18542064, 2008). "The effect of PDK-1 inhibition on cell proliferation and survival by antisense oligonucleotides implicates PDK-1 as a potential therapeutic target for human cancers including RMS." (PMID 17848913, 2007). "PDK-1 and its downstream target AKT are frequently phosphorylated and activated in multiple types of cancers." (PMID 17848913, 2007). "Constitutive activation of PI3-K/PDK-1/AKT signalling mediates the survival signals and confers resistance to apoptosis induced by anticancer cytotoxic agents in human cancer cells." (PMID 17848913, 2007). "Additionally, ilimaquinone inhibits pyruvate dehydrogenase kinase 1 (PDK1), reducing aerobic glycolysis and depleting cellular ATP, which sensitizes cancer cells to apoptosis." (PMID 40710508, 2025). "In summary, our study has pioneered a novel therapeutic approach centered on PDK1 degradation rather than enzymatic activity inhibition, achieving significant success in cancer immunotherapy." (PMID 40873633, 2025). "In addition, a mutation within the PH domain of Akt (E17K), reported in various cancer settings, shows stronger Akt binding to PIP3 and increased PDK1 phosphorylation, contributing to cell proliferation in cancer." (PMID 41032702, 2025). "In PTEN-mutant cancer cells with high AKT activity, PI3K utilizes PDK1 and AKT signals." (PMID 40427140, 2025). "When the expression level of PDP1/PDH is too low under hypoxia, subsequent inhibition of HIF1A transcriptional activity and a reduction in its target gene, pyruvate dehydrogenase kinase 1 (PDK1), partially restore the activity of PDH for cancer cell proliferation." (PMID 39776803, 2025). "Proteasome inhibitor MG132 paradoxically reduced the abundance of PDK1 in human cancer cells and rat L6 myotubes, suggesting that MG132 might direct PDK1 towards autophagic degradation." (PMID 39080182, 2024). "The LIN28/let‐7 axis has been reported to facilitate aerobic glycolysis to promote cancer progression.[14b] In this study, PIWIL2 overexpression in HaCaT cells induced LIN28 upregulation, particularly that of LIN28A, and PDK1, which also were observed in HCBC stably transfected with PIWIL2 or E6." (PMID 39499767, 2024). "The upregulation of PDK1 by HIF-1α under hypoxic conditions is important for the inactivation of the pyruvate dehydrogenase complex, which switches glucose metabolism from oxidation to lactate formation in cultured fibroblasts and cancer cells." (PMID 39080182, 2024). "Based on the concerted action of MAPK4-AKT and MAPK4-PDK1 axis in promoting cancer, we predict and confirm that co-targeting AKT and PDK1 effectively represses MAPK4-induced cancer cell growth, suggesting a potential therapeutic strategy to treat MAPK4-high cancers." (PMID 37531320, 2023). "Herein we highlight the biology and biochemistry of the PAM axis, describe its major dysregulations in cancer, show its main crosstalks with other signaling pathways, and discuss PI3K-, AKT-, mTOR-, and PDK1-targeted inhibitors, emphasizing on their mechanisms of therapeutic resistance." (PMID 37596643, 2023). "We recently reported that MAPK4 can promote cancer by noncanonically activating AKT independent of the PI3K/PDK1 signaling axis." (PMID 37531320, 2023). "Therefore, to protect cancer cells from harmful ROS, HIF-1α activates PDK-1, impairs the Kreb cycle, thereby reducing NADH flux to the electron transport chain and generating ROS." (PMID 36891273, 2023). "We have previously documented that MAPK4 can directly activate AKT independent of the canonical PI3K/PDK1 pathway to promote cancer growth." (PMID 37531320, 2023). "Besides enhancing resistance to PI3K blockade, MAPK4 also promotes cancer cell resistance to the more stringent PI3K and PDK1 co-blockade, a recently proposed therapeutic strategy." (PMID 37531320, 2023).
cancer (continued). "In fact, cancer cells may be more dependent on isoforms of hexokinase (HK2), pyruvate dehydrogenase kinase 1 (PDK1), phosphofructokinase 2 (PFK2), LDHA or pyruvate kinase isoform M2 (PKM2)." (PMID 38004589, 2023). "In contrast, how MAPK4 affects cancer cell response to the more stringent co-blockade of PI3K and PDK1 remains unknown." (PMID 37531320, 2023). "We predict that the MAPK4-AKT axis may also sustain AKT phosphorylation/activation and provide MAPK4-high cancer cells resistance to combined PI3K and PDK1 inhibitors treatment." (PMID 37531320, 2023). "Cancer cells show aerobic glycolysis, the well-known Warburg effect, and dichloroacetate (DCA) diverts the glucose utilization from aerobic glycolysis to respiration by inhibition of mitochondrial pyruvate dehydrogenase kinase 1 (PDK1)." (PMID 36048281, 2022). "The Wnt/β-catenin pathway is also involved in the reprogramming of cancer metabolism, where it directs cells into glycolysis and away from mitochondrial OXPHOS, through the regulation of PDK1 expression and by reducing the conversion of pyruvate into acetyl-CoA." (PMID 36497394, 2022). "Moreover, ALDHs are markers of cancer stem-like cells and regulate signaling transduction, such as canonical RA signaling, c-MYC, cyclinD1 and PDK1/AKT." (PMID 36300093, 2022). "PDK1 is also considered constitutively active in cancers because its activation site (serine 241) is activated by PDK1 itself and not by other kinases." (PMID 34768921, 2021). "Problem 1 asked participants to predict molecules that bound the RETM955T-associated cancer pro-targets RET[M918T], BRAF, SRC, S6K, and did not bind the anti-targets MKNK1, TTK, ERK8, PDK1, and PAK3." (PMID 34520464, 2021). "Alterations in the PDK1 mRNA and protein levels were not always in correlation, which was especially evident in PC-3 cancer cells and L6 myotubes." (PMID 34445316, 2021). "Thus, the findings identify a novel regulatory crosstalk between the Nedd4l‐CTR1‐copper axis and the PDK1‐AKT oncogenic signaling, and highlight the therapeutic relevance of targeting the CTR1‐copper node for the treatment of hyperactive AKT‐driven cancers." (PMID 34278744, 2021). "The DCA-induced PDK1 suppression was partially dependent on hypoxia-inducible factor-1α (HIF-1α), a transcriptional regulator of PDK1, in cancer cells but not in L6 myotubes." (PMID 34445316, 2021). "Baicalin impedes EMT by inhibiting the PDK1/AKT pathway in human NSCLC and thus may be an effective alternative treatment for carcinoma and a new candidate antimetastasis drug." (PMID 34868313, 2021). "More studies are needed to decipher whether and how mitochondrial fission influences the apoptosis antagonizing nature of PDK1 in both BRAFV600E CRC and other cancers." (PMID 33738242, 2020). "In line our results demonstrate that PDK1 could be an important glycolytic regulator in BRAFV600E driven CRC and that it also could pose a therapeutic vulnerability to cancers driven via fragmented mitochondrial phenotype." (PMID 33738242, 2020). "Elevated levels of LDHA, PDK-1, and MCT-4 are considered hallmarks of cancers with Warburg Effect." (PMID 31936895, 2020). "Moreover, PDK1 plays a key role in the PI3K-AKT pathway, which is one of the most common deregulations in human cancers." (PMID 30734603, 2019). "In addition, other cancer-drivers/oncogenes, e.g. IGF1, CDK6 and PDK1 that are widely involved in oncogenesis, were also suppressed by TSPX in a CAD-dependent manner." (PMID 30863497, 2019). "The two key enzymes of aerobic glycolysis (Glut4 and PDK1) were found to be up-regulated by Axl/TNS2/IRS-1 cross-talk and may play a critical role in glucose metabolism of cancer cells." (PMID 30419905, 2018). "Here, we reveal that pharmacological inhibition of the cytoplasmic activity of 3-phosphoinositide-dependent protein kinase 1 (PDK1) selectively promotes the formation of the core assembly, but not the purinosome, in cancer cells." (PMID 29668719, 2018).
cancer (continued). "In cancer cells located within the poorly oxygenated regions of solid tumors, coordinate inhibition of ATGL and PDH by HIG2 and PDK1, respectively, should collectively lead to reduced mitochondrial oxidative metabolism and ROS production as well as improved tissue oxygen homeostasis." (PMID 29256392, 2017). "PDK1 triggers the phosphorylation of PLK1, which is also upregulated in many cancers, and the latter interacts with MYC, phosphorylates it and results in its accumulation in cancer cells." (PMID 29064423, 2017). "It is interesting that in a commentary article, Alessi—a leading scientist in the PDK1 research field—and Peifer specifically emphasize that “just because PDK1 is not on many researchers’ radars does not mean it is not a key anti-cancer target”." (PMID 29064423, 2017). "Thus both PIK3CA and PDK1, as well as p-AKT, were potential drug targets in ARID1A-mutant cancer cells." (PMID 27323812, 2016). "PDK1 is believed to be upregulated by Myc and HIF-1 to facilitate cell survival and proliferation under hypoxia, and is reported to be commonly overexpressed in cancer cells." (PMID 26025378, 2015). "Although PDK1 and PDK2 have been previously proposed as cancer drug targets, our findings suggest that PDK4 may function as a metabolic tumor suppressor." (PMID 25379179, 2014). "Indeed, PDK1 is a transducer of PI3K signaling pathway and is a critical component of oncogenic PI3K/Akt activity in some cancers." (PMID 24927102, 2014). "PDK1 is a key component in phosphatidylinositol 3-kinase-Akt-mammalian target of rapamycin (PI3K-Akt-mTOR) signaling, a well-documented pathway that regulates cancer cell survival and proliferation." (PMID 24137444, 2013). "Thus, inhibiting PDK1 would re-activate PDH and restore mitochondrial membrane polarity, thereby facilitating cancer cell apoptosis in response to chemotherapeutic agents and radiation." (PMID 24212624, 2011). "Inhibition of LDHA or PDK1 using the chemical inhibitors oxamate and dichloroacetate (DCA) respectively, has been shown to counter the Warburg effect and apoptosis resistance in cancer cells." (PMID 21541279, 2011). "Moreover, inhibition of PDK1 expression has been shown to decrease lactate levels and HIF-1α expression and reduce the malignant phenotype of cancer cells." (PMID 21541279, 2011). "These include PDK1 inhibitors (to prevent AktT308 phosphorylation and non-PI3K dependent phosphorylation of other kinases that can promote cancer progression), SHIP agonists (to promote PIP3 degradation), and heat shock protein inhibitors (Akt is a client protein of the molecular chaperone)." (PMID 21317449, 2010). "Not previously reported was the finding that PDK-1 demonstrated nuclear expression in a subset of cancers." (PMID 18542064, 2008). "Additionally, PDK1 is a mediator of the PI3K/AKT pathway, and the activation of this axis may contribute to the resistance of the cancer cells." (PMID 40759693, 2025). "Moreover, caffeine downregulates the expression of several proteins, including retinoblastoma protein (Rb), extracellular signal-regulated kinases (ERK) 1/2, GSK3β, pyruvate dehydrogenase kinase 1 (PDK1), cyclin D1, cyclin E, c-Myc, Akt, and mTOR in various cancer cell lines." (PMID 39064880, 2024). "Here, we connect dysregulated signaling in the MAPK and PI3K/PDK1/AKT/mTOR (where PDK1, phosphoinositide-dependent protein kinase 1; mTOR, mammalian target of rapamycin) pathways with dysregulated cell cycle subverting normal cell proliferation and differentiation, resulting in NDDs or cancer." (PMID 37124926, 2023). "Since PDK1 is a critical enzyme that regulates glycolytic metabolism in cancer cells and our results have demonstrated that PDK1 is regulated by FOXM1, we next sought to determine whether PDK1 is involved in the elevated glycolysis and cell proliferation rates regulated by FOXM1." (PMID 35656815, 2022).